EDN1 (endothelin 1)
Diseases named in the same sentence as EDN1 in open-access papers (continued):
Sharing a sentence is not in itself a finding about the gene and the disease.
diabetes (continued). "Once damaged by disease conditions, such as diabetes, the resultant hyperglycemic condition promptly induces the production of TGFβ in mesangial cells, which in turn promotes endothelin-1 formation in podocytes." (PMID 27683034, 2016). "On the other hand, endothelin-1 (ET-1), a potent vasoconstrictor peptide, is potentially involved in the vasomotor dysregulation of patients with diabetes as well as in the development of their vascular complications." (PMID 27376035, 2015). "The aim of this study was to evaluate the association between genetic variants of the ET-1 and ETRA genes (EDN1 and EDNRA) and DKD in patients with type 2 diabetes mellitus (T2DM)." (PMID 26594247, 2015). "In the present study, the association of DKD with polymorphisms in ET-1 (EDN1) and ETRA (EDNRA) genes was analyzed in patients with type 2 diabetes mellitus (T2DM)." (PMID 26594247, 2015). "Similar to AGT, we found that EDN1 mRNA levels were also increased in diabetes, an effect that was normalized in the miR-133a/D group." (PMID 24428157, 2014). "In our current study, we show that p300 mRNA levels increase with diabetes and this increase was correlated with an increase in mRNA levels of fibrosis inducers: EDN1, AGT, CTGF and TGF-β1, and ECM genes, e.g. COL4A1 and FN1." (PMID 24428157, 2014). "Plasma and urine levels of endothelin-1 are increased in diabetes and after exposure to high doses of contrast media suggesting a role of endothelin-1 in diabetic nephropathy and in contrast-induced AKI." (PMID 25197639, 2014). "Plasma and urine levels of endothelin-1 are increased in diabetes and after exposure to high doses of contrast media; this has suggested a role of endothelin-1 in diabetic nephropathy and in CIN." (PMID 25525625, 2014). "Endothelin-1 (ET-1), a potent vasoconstrictor with profibrotic properties, is chronically elevated in diabetes." (PMID 22474522, 2012). "In states of oxidative stress as in diabetes increased expression of endothelin 1 has been found paradoxically to restore diastolic dysfunction and endothelin 1 is a known inducer of sST2 expression and inhibitor of IL-33 signaling through p38 MAPK." (PMID 22104207, 2011). "Common agreement exists on the role of excessive neurohumoral stimulation in the pathogenesis of atherosclerotic plaque formation in diabetes, involving angiotensin II and endothelin-1." (PMID 21190563, 2010). "Increased circulating levels of endothelin-1 (ET-1) have been found in patients with diabetes, and a positive correlation between plasma ET-1 levels and microangiopathy in patients with type-2 diabetes has been demonstrated." (PMID 21461356, 2010). "A higher frequency of the Asn/Asn genotype of EDN1 was found in individuals with at least 10 years of diabetes and no retinopathy (controls) compared with DR patients with any duration of diabetes (DR: 2.3%; control: 11.0%; p=0.0002)." (PMID 18806884, 2008). "Multivariable logistic regression analysis showed that EDN1 Asn/Asn was an independent protective factor for DR after adjustment for age, age at onset of diabetes and insulin therapy." (PMID 18806884, 2008). "A case-control study was performed to study the genetic association between DR and polymorphic variants of EDN1 (Lys198Asn), LTA (IVS1–80C>A, IVS1–206G>C, IVS1–252A>G), eNOS (Glu298Asp), and ITGA2 (BgI II) in a Chinese population with type 2 diabetes mellitus." (PMID 18806884, 2008). "Increased expression of endothelin-1 (ET-1), the mostpotent vasoconstrictor, has been shown in diabetes." (PMID 18288248, 2007). "Furthermore, urinary biomarkers associated with increased endothelin-1 levels have been shown in all causes of CKD, including diabetes, hypertension, glomerular disease and polycystic kidney disease." (PMID 38660120, 2024). "Therefore, we used type 2 diabetes mellitus (T2DM) mice to aggravate endothelin-1 (ET-1)-induced focal cerebral ischemia damage in the brain." (PMID 36615583, 2023).
diabetes (continued). "In conclusion, the present study shows for the first time that administration of the adeno-associated virus containing glyoxalase-1 driven by the endothelin-1 promoter (AAV2/9-Endo-Glo1) to rats one week after onset of T1DM, attenuated the cardiomyopathy that develops after eight weeks of diabetes." (PMID 32640624, 2020). "Results of these studies show that hypoxia is involved in cerebral edema, tumorigenesis, myocardial ischemia and diabetes in human being, and some genes including Endothelin 1 (EDN1), Erythropoietin (EPO) and Aldosterone synthase (CYP11B2) are reported as the key genes of hypoxia adaptation." (PMID 31239472, 2019). "Furthermore, SIRT1 overexpression has been also shown to be protective in diabetes-induced renal and retinal injury in diabetic mice, through attenuated p300, endothelin-1 (ET-1), and TGF-β1 expression." (PMID 29085333, 2017). "Increased levels of vasoactive peptides, e.g., endothelin-1, in patients with diabetes might further impair microvascular reactivity in these patients." (PMID 27095564, 2016). "Endothelin 1 (ET-1) and transforming growth factor β1 (TGF-β1) are two such vasoactive and growth factors, which have been implicated in the development and progression of several vascular diseases including diabetes 8–14." (PMID 25753689, 2015). "Vasoactive factors including endothelin-1 (ET-1) and angiotensin II are involved in diabetic vascular remodeling as evidenced by studies that demonstrated attenuation of these responses by blockade of these systems in both experimental and clinical diabetes." (PMID 16503991, 2006). "Diabetes-related hemodynamic effects include elevated systemic and intraglomerular blood pressure, causing hyperfiltration that drives progressive albuminuria and a decline in GFR, influenced by circulating mediators such as angiotensin II (Ang II), thromboxane A2, and endothelin-1 (ET-1)." (PMID 39684653, 2024). "The concentration of endothelin-1, among other things, increases in response to the insulin-mediated effects of increased gene expression and receptor synthesis and as a consequence of the increased presence of glycosylation products, so its vaso-active effects in diabetes are multiple and complex." (PMID 35216512, 2022). "Similarly, short-term treatment of curcumin significantly attenuates diabetes-induced levels of vasoactive factors (endothelin-1 and eNOS), TGF-β1, ECM proteins (fibronectin), and oxidative stress markers (heme oxygenase-1, nitrotyrosine, and 8-OHdG) in kidneys." (PMID 31920992, 2019). "Therefore, Dot1a and Af9 as aldosterone-downregulated targets are negative regulators of endothelin-1 transcription in vitro and in vivo, and may be considered as new potential therapeutic targets of kidney injury in diabetes." (PMID 23077601, 2012). "Endothelin-1 (ET-1), an endogenous vasoconstrictor, also plays a significant role in coronary artery disease (CAD) and diabetes." (PMID 41302503, 2025). "Furthermore, in some diseases, such as diabetes mellitus, endothelin-1 secretion might promote more pronounced efferent arteriolar constriction, which in concert with other vascular factors and tubular signals affecting the afferent and efferent arterioles, might lead to glomerular hyperfiltration." (PMID 38660120, 2024). "Complications in diabetes can be regulated by PKC at multiple levels such as via activation of eNOS, NAD(P)H oxidase, phospholipase A2 (PLA2), endothelin-1 (ET-1), vascular endothelial growth factor (VEGF), transforming growth factor-β (TGF-β) and NF-κB." (PMID 35164215, 2022). "Increased renal endothelin‐1 (ET‐1) production and an ETA receptor‐dependent increase in glomerular albumin permeability (Palb) accompany type 1 diabetes mellitus (T1D)." (PMID 28039404, 2016). "Endothelin-1 (ET-1) and matrix metallopeptidase-9 (MMP-9) have been implicatedin the development of cardiovascular diseases, diabetes mellitus and cancers." (PMID 26692905, 2015).
diabetes (continued). "The high glucose (HG) induced by diabetes stimulates the activation of the renin-angiotensin-aldosterone system (RAAS), upregulates sodium-glucose cotransporter-2 (SGLT-2) receptor, and secretes endothelin-1 (ET-1)." (PMID 39201721, 2024). "In addition, the imbalance of vasoconstrictors, such as endothelin-1, and a lower availability of vasodilator nitric oxide (NO) as a result of hyperglycemia-driven oxidative stress may lead to poor vasorelaxation, which plays a major role in microvascular and macrovascular problems of diabetes." (PMID 37065258, 2023). "While the EDN1 (endothelin 1) alterations have been well described in DR, induction of EDN2 (endothelin 2), a potent vasoconstrictor, and the endothelin receptor EDNRB (endothelin receptor B) have been described after 6 months of diabetes and light injury." (PMID 18554398, 2008). "Finally, experimental evidence suggests that SARS-CoV-2 induces cardiorenal injury in rats with post-myocardial infarction heart failure and mice with AKI and diabetes by downregulating apelin and ACE2, while upregulating SGLT-2, endothelin-1, and pro-inflammatory cytokines." (PMID 38448675, 2024). "The plasma big endothelin-1 (big ET-1) level is closely related to cardiovascular adverse events; however, for patients with ISR and diabetes who undergo percutaneous coronary intervention (PCI), whether big ET-1 is independently correlated with prognosis is still uncertain." (PMID 35694656, 2022). "The link between the renal artery receptor angiotensin II type I (AT1R) and endothelin-1 (ET-1), involved in vasoconstriction, oxidative stress, inflammation and kidney fibrosis (collagen) in diabetes-induced nephropathy with and without metformin incorporation has not been previously studied." (PMID 35884947, 2022). "Additionally, nitric oxide (NO), endothelin-1 (ET-1), vasopressin, and vascular endothelial growth factor (VEGF) have also been shown to be impaired as regulators of kidney vascular tone in individuals with diabetes." (PMID 34211943, 2021). "From this point of view, increased levels of sST2 in patients with diabetes and LVDD might be an epiphenomenon of other counteregulatory mechanisms such as endothelin 1 or to signify patients with failure of IL-33-induced cardioprotection, through sST2 acting as a decoy receptor." (PMID 22104207, 2011). "C-peptide treatment was ineffective in preventingthe diabetes-induced increase in capillary BM thickness.The authors' previous studies of cultured endothelialcells demonstrated that oncofetal FN synthesis is, atleast in part, mediated via transforming growth factor-β(TGF-β) and endothelin-1 (ET-1)." (PMID 15198374, 2004). "We created a scoring system by using diabetes mellitus status (yes = 2, no = 0) and the median levels of MMP-2 (2 vs. 0), galectin-3 (1 vs. 0) and endothelin-1 (2 vs. 0), as cut-off points." (PMID 30413105, 2018). "We observed an up-regulation of inducible nitric oxide synthase (iNOS), prepro endothelin-1 (preproET-1) and phosphorylated p38-MAPK in thoracic aorta and kidney cortex but not in kidney medulla in 28-days diabetes group." (PMID 15748291, 2005).
Stroke (166 papers, 2009 to 2026). Sudden impairment of blood flow to a part of the brain due to occlusion or rupture of an artery to the brain. "Endothelial cells are damaged and secrete the vasoconstrictive endothelin-1 that is associated with a poor prognosis after stroke." (PMID 35054890, 2022). "A recent case–control study demonstrated that polymorphisms in the Endothelin 1 gene increase stroke risk, and in animal models of middle cerebral artery occlusion, over-expression of endothelin produced increased brain edema and ischemic brain injury." (PMID 23459313, 2013). "Recently, we reported that lysolecithin (LPC)-induced demyelination at the internal capsule (IC) resulted in acute motor deficits, followed by subsequent remyelination-associated functional recovery, whereas an endothelin 1 (ET1)-induced stroke model resulted in lasting motor deficits." (PMID 40221393, 2025). "The level of endothelin-1, a vasoconstrictive biomarker produced by endothelial cells, neurons, and glial cells, has been found to increase during the ictal phase of migraine headaches, predisposing patients to stroke through vasoconstriction." (PMID 39148704, 2024). "Variations in genes related to vascular wall structure and function (such as COL3A1, EDN1) may influence stroke risk." (PMID 39655053, 2024). "Stroke history may also increase risk of developing AD, as it was observed in rats in which stroke is induced by striatal injection of endothelin-1." (PMID 33396565, 2020). "Significant association between EDN1 rs5370 and stroke was revealed under dominant (Pc = 0.012; ORc = 1.657, 95% CI = 1.115–2.462), recessive (Pc = 0.007; ORc = 2.839, 95% CI = 1.331–6.057), and additive (Pc = 0.003; ORc = 3.291, 95% CI = 1.512–7.165—for TT genotype) models of inheritance." (PMID 29849817, 2018). "Consistent with this hypothesis, studies evaluating genetic polymorphisms in the vasoconstrictor endothelin-1 gene (EDN1) were associated with increased risk of stroke risk as well as migraine." (PMID 23459313, 2013). "Therefore, endothelin-1 administration can cause additional side effects which could interfere with the experiment outcome, affecting and complicating interpretation of the stroke study." (PMID 41541099, 2023). "Our study focused on the role of traditional Chinese medicine in stroke therapy, specifically targeting endothelin-1 (ET-1) in astrocytes to alleviate ischemic brain injury." (PMID 40453657, 2025). "These EGF-PEG/EPO polymeric particles were administered four days after inducing a stroke-like lesion in 9–11-week-old male mice using cortical endothelin-1 injection, a clinically relevant time point of delivery." (PMID 40558537, 2025). "Third, testing across different stroke models remains crucial, as our study using the endothelin-1 (ET-1) model differs from previous studies of photothrombotic or middle cerebral artery occlusion models." (PMID 40676515, 2025). "Third, vitamin D maintains endothelial function and vascular integrity by upregulating nitric oxide production and reducing endothelin-1, potentially preserving renal microcirculation during post-stroke hypoperfusion states." (PMID 41561180, 2025). "Our results showed that microbiota depletion triggered very low levels of several inflammatory signaling genes such as Myd88, IL-17ra, Edn1 and Stat3 in the ischemic hemispheres of MiD mice compared to MiS stroke mice." (PMID 40410847, 2025). "To understand how post-stroke butyrate supplementation affects microglial responses, we examined microglial number and morphology in male and female mice following endothelin-1-induced stroke at D4 and D20, representative of acute and chronic stroke." (PMID 40676515, 2025). "The research teams discussed in this review have employed various types of animal models for AIS, including transient MCAO, permanent MCAO, the photothrombosis stroke model, and the endothelin-1 induced stroke model." (PMID 40756344, 2025).
Stroke (continued). "Currently, the most commonly used animal models of AIS include: MCAO, photothrombotic stroke model, endothelin-1 model, and embolic stroke model." (PMID 40756344, 2025). "The aim of this study was to investigate the potential role of two vasoactive molecules endothelin-1 (ET-1)—a vasoconstrictor agent—and nitric oxide (NO)—a vasodilator agent—in the regulation of post-stroke LMCs." (PMID 40244012, 2025). "Beginning 2 weeks after the endothelin-1-induced stroke, rats were administered DBS of lateral cerebellar nucleus consecutively for 14 days, followed by morroniside for 7 consecutive days post-stimulation." (PMID 39697542, 2024). "In a more recent study using the rat endothelin-1 model of stroke, the reaching task was performed on experimental day 1, and days 3, 4 and 14 after stroke, and four measurements were taken individually for each rat." (PMID 38674304, 2024). "Endothelin-1 also influences CSD, highlighting its significant role in the pathophysiology of migraine and stroke risk." (PMID 39148704, 2024). "Meanwhile, larger animals demonstrate excellent utility for endothelin-1-based stroke induction, as shown in pigs, and NHPs, including marmosets and rhesus monkeys." (PMID 41541099, 2023). "In line with this, our group has published a set of studies using endothelin-1 (ET-1) as a model of stroke, in order to evaluate the patterns of the inflammatory response, demyelination and cell death in distinct regions of the nervous system." (PMID 36766798, 2023). "The endothelin-1 technique is another stroke model commonly used both in rats and mice, based on the local application of a vasoconstrictor agent." (PMID 36650068, 2023). "The endothelin-1 model was first established in rats and was the first stroke model inducible in conscious animals, with cerebral infarctions comparable to those achieved in anesthetized MCAO models." (PMID 41541099, 2023). "Through local NeuroD1-based gene therapy, our earlier works on stroke succeeded in increasing the neuron number after endothelin-1 induced focal stroke in mice and rhesus monkeys." (PMID 38270116, 2023). "The effects of two structurally distinct IRAP inhibitors (HFI419 or SJM164) were investigated in a model of stroke where the middle cerebral artery was transiently occluded with endothelin-1 in the conscious spontaneously hypertensive rat." (PMID 37957163, 2023). "Similar to the photothrombotic stroke model, endothelin-1 (ET-1) allows for the induction of stroke in an awake animal." (PMID 35163820, 2022). "The most common stroke models included intraluminal suture craniectomy, photothrombosis, endothelin-1, embolic stroke model, and so on." (PMID 35547371, 2022). "We also compared the effect of LPC‐induced IC damage to that produced by endothelin‐1 (ET1), a potent vasoconstrictor used in experimental stroke lesions." (PMID 32750162, 2021). "MEL is effective in the reduction in endothelin-1 (ET-1) concentration in the brain of patients suffering from a stroke." (PMID 33440795, 2021). "Direct evidence for a protective role of ACE2 in stroke includes prevention of cerebral damage and behavioral dysfunction in the endothelin-1 (ET-1)-induced MCAO model by administration of an ACE2 activator Diminazene aceturate." (PMID 34829896, 2021). "In this study, a focal stroke model with a very low mortality rate was employed through intracranial injection of endothelin-1 to induce blood vessel constriction in the motor cortex of rhesus macaque monkeys." (PMID 34124038, 2021). "The most common method for investigating an animal model of ischemic stroke, which accounts for three-quarters of stroke, is by injecting coagulated blood in a particular area or injecting endothelin-1 (ET-1) to close or mechanical vascular occlusion." (PMID 33707580, 2021).